CXCR4 (C-X-C motif chemokine receptor 4)
Diseases named in the same sentence as CXCR4 in open-access papers (continued):
Sharing a sentence is not in itself a finding about the gene and the disease.
cancer (continued). "CXCR4 and VEGF-A were observed in both stromal and cancer cells, and the IHC grades were significantly higher in NPC than chronic nasopharyngeal tissues (CXCR4, P = 0.041; VEGF-A, P = 0.015)." (PMID 24877105, 2014). "High expression of the ligand for CXCR4, CXCL12/SDF-1, is detected in organs that are usually the primary destinations of metastasis for these cancers." (PMID 24941119, 2014). "Compelling evidence revealed that SDF-1/CXCR-4 signal axis was important in the progression and metastatic dissemination of PDAC, especially well known for its recruitment of cancer cells to specific organs." (PMID 24587996, 2014). "CXCR4 and SDF-1 have been investigated as growth and metastasis inhibitors of many different cancers." (PMID 24647809, 2014). "Many cancer cell types specifically express different CC and CXC chemokine-chemokine receptors, including CCR6, CCR9, CXCR4, and CXCR5." (PMID 25296976, 2014). "The CXCR4/CXCL12-axis has been demonstrated to exhibit a critical role in the trafficking and homing of normal stem cells and metastasis of cancer stem cells to organs that express high levels of CXCL12, including the lymph nodes, lungs, liver and bone." (PMID 25202367, 2014). "Hence, in addition to being a prognostic marker, CXCR4 could also be an anti-cancer therapy target." (PMID 24475985, 2014). "To further characterize the signaling pathways involved in CXCR4 expression, we used chemical inhibitors of the MEK-ERK and PI3K signaling pathways on adherent HeyA8 cancer cells." (PMID 25514788, 2014). "CXCR4 and CXCR7 were consistently expressed in normal and cancerous pancreatic ductal epithelium, established cell lines, and patient-derived primary cancer cells." (PMID 24594697, 2014). "Among various biological processes, CXCR4 plays a critical role in WHIM syndrome, HIV entry, cancer progression and metastasis." (PMID 25514788, 2014). "Moreover, each cancer type might require a different CXCR4 antagonist, exploiting pharmacological features such as oral availability and pharmacokinetics, and the prevalent ability to mobilize hematopoietic cells or to inhibit metastasis or invasion of cancer cells." (PMID 24904289, 2014). "Several groups found that CXCR4 and its ligand CXCL12 can promote the proliferation, survival, and invasion of cancer cells." (PMID 24810923, 2014). "The chemokine receptor CXCR4 and its ligand CXCL12, also known as stromal cell-derived factor 1 (SDF-1), are attractive therapeutic targets in the treatment of cancer, as they support migration, proliferation, and survival of cancer cells." (PMID 24966838, 2014). "Previous studies have confirmed a relationship between CXCR4 and HIF-1α expression in different cancers." (PMID 24618817, 2014). "The chemokine network and CXCL12/CXCR4 signaling in particular, as well as EGFR signaling are involved in many aspects of cancer biology, including growth and metastasis." (PMID 24906407, 2014). "Analysis of a cohort of colon polyps and chromosome-unstable carcinomas showed that the expression of CXCR4 and CXCR7 was similar to that of the normal mucosa in the early-stage but significantly increased from early to late stage carcinomas." (PMID 24629239, 2014). "While naïve T cells express several chemokine receptors, including CXCR4 and CCR7, CCR7 is uniquely important in driving the homing of cells to lymph nodes, including naïve T cells, dendritic cells, and cancer cells." (PMID 24250818, 2013). "A CXCR4 peptide can be modified at position 21 by expression of TPST-1, but the mechanisms of TPST-1 activation and function in cancer remain enigmatic." (PMID 23472069, 2013). "CXCR4 is highly expressed in AML, and interactions between CXCR4 and its ligand CXCL12, constitutively secreted by BM stromal cells, promote proliferation, survival, migration, and homing of cancer cells." (PMID 23826077, 2013).
cancer (continued). "The expression levels of CCR7, CXCR4 and VEGF-C mRNA in the cancer samples were all significantly higher than those in the adjacent normal tissue." (PMID 23761820, 2013). "The mRNA and protein expression levels of CCR7, CXCR4 and VEGF-C were all significantly higher in the cancer samples compared with those in the adjacent normal tissue." (PMID 23761820, 2013). "As previous studies have demonstrated that ERK1/2 phosphorylation occurs through CXCR4 activation, the present study focused on ERK1/2, which is significant in regulating the malignant potential of cancer cells." (PMID 24179538, 2013). "Invasive cancer showed pooled expression rates of 35% for CAIX (95% confidence interval (CI): 26-46%), 51% for GLUT1 (CI: 40-61%), 46% for CXCR4 (CI: 33-59%), and 46% for IGF1R (CI: 35-70%)." (PMID 24206539, 2013). "Because of the critical role that the CXCL12/CXCR4 axis plays in HIV infection and cancer metastasis, it has served as an important target in the development of antitumoral and anti-HIV-1 therapies." (PMID 23987636, 2013). "Amongst the chemokine signalling axes involved in cancer, chemokine CXCL12, acting on chemokine receptor CXCR4 is particularly significant." (PMID 24205302, 2013). "CXCR4 and CAIX also show higher expression in grade III cancers, but for CAIX expression prevalence is markedly lower in smaller lesions." (PMID 24206539, 2013). "It was demonstrated that the expression levels of CCR7, CXCR4 and VEGF-C mRNA and protein were all significantly higher in the cancer specimens compared with those in the adjacent normal tissue." (PMID 23761820, 2013). "Chemokine receptors CXCR4 and CXCR7 play important roles in progression of various cancers although the specific functions of the CXCL12−CXCR4−CXCR7 axis in GBM are less characterized." (PMID 23555768, 2013). "Compared with CD133+CXCR4- cells, CD133+CXCR4+ cancer cells have a high metastatic capacity in vitro and in vivo and undergoes epithelial-mesenchymal transitions (EMT)." (PMID 23815814, 2013). "In conclusion, microglia have less influence on MDCK apoptosis than on invasion of the carcinoma cells, for which the effects of WNT or CXCR4 inhibition as well as microglia depletion are more pronounced." (PMID 23832647, 2013). "Several studies have identified the relationships among CXCR4, CXCR7 and SDF-1 and the clinical and histopathological parameters of various cancer types as well as patient prognosis." (PMID 23039915, 2012). "Similar to what is known about CXCR4, recent reports have indicated that CXCR7 promotes cancer cell survival through anti-apoptotic mechanisms." (PMID 22472349, 2012). "CXCR4, the specific receptor of CXCL12, is highly-expressed in cancer cells compared with homological normal tissue." (PMID 23443093, 2012). "HIF-1α, being the best characterized inducer of gene transcription in hypoxic cells, is overexpressed in various cancer types including EWS, and a key role for this protein in hypoxic induction of CXCR4 has been described." (PMID 23249693, 2012). "The expression of CXCR4, CXCR7 and SDF-1 between carcinoma tissues (CT) and the surrounding tissues (ST) was compared." (PMID 23039915, 2012). "Metastasis is characterized by the ability of cancer cells to invade adjacent tissue, and is regulated by multiple signaling pathways, including the CXCL12/CXCR4 axis." (PMID 22074556, 2011). "Increasing evidence indicates that the interaction between the CXC chemokine receptor-4 (CXCR4) and its ligand CXCL12 is critical in the process of metastasis that accounts for more than 90% of cancer-related deaths." (PMID 21880153, 2011). "CXCR4 (fusin) is a CXC chemokine receptor which is expressed in all leukocytes, blastocysts and a variety of cancer cells." (PMID 22087325, 2011).
cancer (continued). "Moreover, coculture of cancer stem cells with pancreatic stromal cells which express CXCL12 was associated with an increased migration and invasion ability of cancer stem cells, and these effects were significantly reduced by CXCR4 downregulation using RNA interference." (PMID 24212636, 2011). "Plerixafor was initially developed to interfere with SDF-1/CXCR4 interaction and shows promise for HIV infection, cancers and autoimmune diseases such as rheumatoid arthritis." (PMID 22087325, 2011). "Epigenetic drugs can affect many genes and multiple pathways, including some capable of inducing cancer cell migration and invasion, such as CCR7, CXCR4, uPA and ROS." (PMID 20856924, 2010). "Studies have ultimately attributed the abnormal activation of NF-κB in cancer cells to the excessive secretion of TNF-α, whose role in CXCR4 upregulation is subsequently assumed to be related to pathways mediated by NF-κB." (PMID 20699000, 2010). "The selective hyperactivation of p38 MAPK signalling in NSCLC (and other cancer types) has been correlated to malignant transformation via the induction of MMP-2 and CXCR4/SDF-1 chemotaxis axis." (PMID 20226009, 2010). "In other types of cancer the physiological role of CXCR4/CXCL12, carried out during the embryonic development, is turned in the ability to influence cell migration and spreading in cancer." (PMID 20049170, 2010). "In agreement with CXCR4, upregulation of CXCR7 enhances the metastatic potential of several carcinomas." (PMID 20877573, 2010). "This is of particular interest in drug development strategies as both CXCR4 and STAT3 antagonisms have been proposed as broad spectrum target in cancer therapy." (PMID 19455144, 2009). "Organs to which these cancers metastasize secrete CXCL12, the unique ligand for CXCR4, which stimulates invasion and metastasis to these sites." (PMID 19325924, 2009). "This potent molecule is not only chemotactic for the bone marrow derived haematopoietic progenitor cells shown to be critical to the development of the premetastatic niche, but also for cancer cells that often express the cognate receptor for SDF-1, CXCR4." (PMID 19383172, 2009). "We compared 231-control cells to MDA-MB-231 cells stably expressing CXCR4 (231-CXCR4) or CXCR7 (231-CXCR7) to assess effects of CXCL12 chemokine receptors on cancer cells in mediating adhesion onto the microfluidic endothelium." (PMID 19484126, 2009). "Having established the role of CCL20 in cancer development in vivo, we evaluated the effect of neutralizing antibodies to human CCL20 on the growth of CCL20-and CXCR4 overexpressing PC3 cells." (PMID 19340288, 2009). "One of the best studied chemokine receptors is CXCR4, primarily because of its role as a coreceptor for HIV entry as well as its ability to mediate the metastasis of a variety of cancers." (PMID 19002187, 2008). "Concomitan high expression of CXCR4 and VEGF has beenobserved in colorectal, breast, and ovarian cancers, as wellas in glioma and osteosarcoma, in each of which it has been linkedto increased angiogenesis, invasion, and/or metastasis." (PMID 18779872, 2008). "As with hematopoietic progenitor cells, release and homing of certain cancer cells require adhesion molecules and Gαi-coupled GPCRs (such as VLA-4, CXCL12/CXCR4)." (PMID 18534032, 2008). "Recent reports suggest a role for CXCR4 and its ligand CXCL12 in the malignant behaviour of cancer cells." (PMID 17925864, 2007). "In order to confirm the observed translocation in human carcinoma cells we used HT29 cells, which had previously revealed a strong CXCR4 expression and an intact CXCR4 receptor." (PMID 16819541, 2006). "The binding interactions between immobilized antibodies and EVs isolated from different cancer cell lines revealed a unique SPR molecular fingerprint (SPR-MFP) consisting of varying expression levels of the CD9, CD63 and CD81 EV biomarkers, as well as CXCR4." (PMID 41892066, 2026).
cancer (continued). "Due to their nature as druggable membrane receptors, CXCR4, S1P1 and S1P5, they might be exploited in potential cancer therapies, as illustrated by the current availability of drugs in the clinic." (PMID 40155684, 2025). "In fact, although the importance of CXCR4 in cancer is widely demonstrated, currently no small molecules are used for this purpose in clinical practice." (PMID 40142155, 2025). "The combined treatment with a specific CXCR4 antagonist, AMD3100, and an AKT inhibitor, GSK690693, synergistically impeded the progression of GBM cells, suggesting novel potential therapeutic strategies for this cancer." (PMID 41041071, 2025). "CXCR4, the receptor for CXCL12, is also being targeted for cancer therapy in the clinic." (PMID 39780187, 2025). "As a chemokine with a crucial function in cancer progression, CXCL12 could bind to CXCR4 and induce multiple signaling pathways related to angiogenesis, cancer progression and metastasis." (PMID 39741182, 2025). "Notably, chemokines such as CXCR4 and CCL20, both located within the pink module, are known to promote carcinogenesis, angiogenesis, and the survival of cancer cells." (PMID 41357186, 2025). "This process confers cancer cells the capacity to intravasate, enter the bloodstream, and extravasate, thereby contributing to homing, colonization and metastasis in organs that secrete CXCL12/SDF-1, the ligand of the chemokine receptor CXCR4." (PMID 40307933, 2025). "Furthermore, these compounds disrupt key molecular pathways like the CXCR4/CXCL12 axis, which is crucial for cancer cell migration and metastasis." (PMID 40018013, 2025). "Moreover, TAM recruitment was found to be influenced by immune-related genes such as CCL2, CCR2, CXCR4, and CCR5, which suppress immune responses and facilitate cancer progression." (PMID 39968182, 2025). "Although there are currently no FDA-approved CXCR4-targeted drug delivery systems for cancer, significant efforts are being made in the scientific community to develop such systems due to their huge potential to revolutionize advanced cancer therapies." (PMID 40307933, 2025). "Additionally, Burixafor (also known as GPC-100 or TG-0054), is another molecule based on the cyclic bicyclam structure that has shown greater affinity for CXCR4 than AMD3100, with potential in cancer therapy." (PMID 40307933, 2025). "The CXCR4/CXCL12 axis is key in mediating drug resistance in TNBC via a multi-pronged mechanism of action, including pro-survival signalling, induction of EMT, maintenance of cancer stem cells, immune suppression, and metastatic dissemination." (PMID 41002447, 2025). "It has been shown that TA interferes with several critical pathways involved in cancer development and progression, including NF-κB, PI3K/AKT, ERK1/2, Wnt/β-catenin, JAK/STAT, RAS/RAF/mTOR, TGF-β1/TGF-β1R axis, VEGF/VEGFR signaling and CXCL12/CXCR4 axis." (PMID 41009634, 2025). "The system was used to illustrate paracellular trans-endothelial migration of individual cancer cell expressing CXCR4, without degrading the endothelium, in response to CXCL12 chemokine gradients." (PMID 39459070, 2024). "Moreover, the inhibition of CXCR4 by WZ811 resulted in decreased mRNA expression levels of MMP3, which is a protein involved in cancer-induced bone lesions." (PMID 38474372, 2024). "Various cancers, including glioblastoma, prostate cancer, breast cancer, lung cancer, multiple myeloma, cervical cancer, and pancreatic cancer, exhibited increased proliferation in response to CXCL12/CXCR4 in a concentration-dependent matter." (PMID 39409924, 2024). "Both, CXCR4 and CXCR7 demonstrated a prominent presence on all of the different cancer cells." (PMID 39420354, 2024). "Understanding the relationship between the CXCL12/CXCR4/ACKR3 axis and the STAT3 pathway could lead to new therapeutic targets for innovative cancer treatments." (PMID 38920657, 2024).
cancer (continued). "The expression of CXCR4 in the adjacent tissues was low or none, and the expression of CXCR4 was significantly different between cancer and adjacent tissues (P < 0.001)." (PMID 38524630, 2024). "Overall, this significant preclinical and clinical evidence raises interest in CXCR4 treatments to inhibit cancer progression, in combination or not with chemotherapy and/or checkpoint inhibitor therapies." (PMID 39596815, 2024). "Despite the interest in using CTCE-9908 as a CXCR4 inhibitor for its anti-tumoural, anti-angiogenic, and anti-metastatic effects in different cancer preclinical models, the peptide has never been radiolabelled before." (PMID 39008219, 2024). "Bone marrow aspirates from patients following BL-8040 treatment demonstrated an approximately 73% decrease in CXCR4 BL-8040-occupied AML blasts from pre-treatment levels, indicating that the treatment effectively mobilized cancer cells from the bone marrow to the peripheral blood." (PMID 38612911, 2024). "Besides the CXCR4/CXCL12 axis, different chemokine receptors have also been shown to play a role in cancer." (PMID 39698539, 2024). "While the role of chemokines in cancer has been extensively studied, only three chemokine-targeting drugs have received FDA approval to date: maraviroc, which targets CCR5; plerixafor, which targets CXCR4; and mogamulizumab, which targets CCR4." (PMID 39409924, 2024). "In a phase I study in healthy volunteers (NCT01374503), ALX-0651 demonstrated appreciable CXCR4 targeting ability; however, the study and any subsequent investigations into ALX-0651 as an anti-cancer agent were halted due to an inability to outcompete other CXCR4 antibodies." (PMID 38612911, 2024). "Thus, the aim of this pilot study was to explore the utility of [68Ga]Ga-Pentixafor in patients with cancer of the head and neck and to compare this novel tracer with [18F]F-FDG on PET/CT imaging as well as CXCR4 immunohistochemistry staining." (PMID 39001265, 2024). "Further, cancer cells can upregulate the production of CCR7/8 and CXCR4/5, which interact to the corresponding receptors from the lymph node namely CCL1/21 and CXCL10/12 respectively, resulting in the migration of cancer cells to the lymphatic vessels by chemotaxis." (PMID 38940900, 2024). "Through a variety of mechanisms, including the direct recruitment of MDSC, the synthesis of GM-CSF in oncogene-driven cancer cells, the stimulation of the epithelial-mesenchymal transition, and the production of VEFG and chemokines (such as CXCL12 and CXCR4), IL-17 exerts a pro-tumorigenic effect." (PMID 38139369, 2023). "Although CXCR4 is highly overexpressed in a variety of cancers, CXCR4 expression does not correlate with poor OS in many cancer types." (PMID 37749552, 2023). "In contrast, FMRP‐KO cancer cells could recruit CCR5+ and CXCR4+ CD8 T cells to indirectly kill cancer cells by promoting M1 macrophages to secrete proinflammatory chemokines CCL5, CXCL9, and CXCL10." (PMID 36968189, 2023). "Our dimeric structures pave the way to the structure-based design of ligands capable of modulating the formation of CCR5 and CXCR4 dimers and, in turn, their activity, with therapeutic potential against HIV, cancer, and immune-inflammatory diseases related to these chemokine receptors." (PMID 37833254, 2023). "Moreover, TAM recruitment depends on immune-related genes such as CCL2, CCR2, CXCR4, and CCR5, which can promote cancer development by promoting immunosuppression." (PMID 37275880, 2023). "Only one treatment for CXCR4 has been approved by the FDA (Mozobil, for hematopoietic stem cell mobilization), and many other treatments for this target are now under development for cancer and other conditions." (PMID 36992255, 2023). "Although the anti-cancer activity of curcumin is widely studied, it is necessary to investigate its capacity to reshape the breast TME by modulating the intricate network of downstream signaling pathways related to the CXCL12/CXCR4 axis." (PMID 38004606, 2023).